TNF (tumor necrosis factor)
Diseases named in the same sentence as TNF in open-access papers (continued):
Sharing a sentence is not in itself a finding about the gene and the disease.
chronic obstructive pulmonary disease (continued). "Besides, the association between dietary intake of omega-3 FAs and serum levels of TNF-α has been established in chronic obstructive pulmonary disease." (PMID 30649643, 2019). "Paradoxically, there is also evidence available from animal studies indicating that TNF-α is involved in the recovery of muscle function after muscle injury and in a human study of chronic obstructive pulmonary disease, levels of quadriceps TNF-α correlated positively with muscle function." (PMID 24147095, 2013). "It has long been recognised that TNF-α is associated with muscle degradation and loss of muscle mass in inflammatory conditions such as cancer, AIDS and chronic obstructive pulmonary disease but the levels of TNF-α are much higher than those found in our study." (PMID 24147095, 2013). "Foamy macrophages contribute significantly to the chronic inflammatory milieu of chronic obstructive pulmonary disease (COPD) by releasing pro-inflammatory cytokines such as IL-6, TNF-α, IL-1α, and IL-1β." (PMID 41009372, 2025). "MgIG (0.80 mg/kg/day) significantly reduced the concentration of IL-6 and TNF-α at the lung and serum levels in rats with experimentally induced chronic obstructive pulmonary disease COPD." (PMID 41597294, 2025). "It was confirmed through in vitro and in vivo experiments that ergosterol reduces ROS, IL-6, and TNF-α, demonstrating anti-inflammatory and anti-senescence properties in managing chronic obstructive pulmonary disease (COPD)." (PMID 40559397, 2025). "Analysis of primary bronchial epithelial cells (PBECs) from patients with severe chronic obstructive pulmonary disease (COPD) revealed significantly elevated TNF-α and IFN-γ levels, reduced IL-4 and IL-13 levels, and elevated Th1-dominated cytokine responses." (PMID 38495892, 2024). "The ethanol extract of the tuber of A. orientale Juzepzuk (EEAO) relieved the pathological features of chronic obstructive pulmonary disease (COPD) by suppressing lung emphysema and autophagy and inducing TNF-α, IL-6, and TGF-β in a mouse model." (PMID 38166725, 2024). "It should be noted however, that these findings do not exclude a role of TNF in human patients with SCLC associated with comorbidities such as chronic obstructive pulmonary disease, where lung inflammation may contribute to tumor progression." (PMID 36653597, 2023). "Further TNFα suppression by resveratrol was observed in several other clinical conditions like chronic obstructive pulmonary disease (COPD), Type 2 Diabetes mellitus and CVD (cardiovascular disease)." (PMID 34066427, 2021). "Interleukin (IL)-1α, IL-1β, IL-6, IL-8 and tumor necrosis factor (TNF)α contribute to inflammation in chronic obstructive pulmonary disease (COPD)." (PMID 33266187, 2020). "In fact, chronic obstructive pulmonary disease (COPD) patients exhibit high TNF-α levels in skeletal muscle, which correlates with lower PGC-1α levels." (PMID 32215168, 2020). "Firstly, in adults with chronic obstructive pulmonary disease (COPD), higher levels of LL-37, IL-8, TNFα and greater inflammatory infiltrate were found in sputum with culturable NTHi compared to culture-negative sputum." (PMID 31877198, 2019). "Interestingly, TNF is linked to upregulation of Purkinje cell protein-4 (PCP4), a putative regulator of calmodulin and Ca2+/calmodulin-dependent kinase II (CaMKII) signaling, within the His-Purkinje network and contributor to cardiac arrhythmias." (PMID 29556499, 2018). "Blood level of TNF-α also remained significantly higher in patients with PE and chronic obstructive pulmonary disease (COPD)." (PMID 27798647, 2016). "TNF-α mediated inflammation is thought to play a key role in both the respiratory and systemic features of Chronic Obstructive Pulmonary Disease (COPD)." (PMID 21985478, 2011).
chronic obstructive pulmonary disease (continued). "A total of 379 targets related to BHC and 7391 targets related to COPD were obtained, including 313 potential targets of BHC in treating chronic obstructive pulmonary disease, with JUN, AKT1, TNF, IL6, EGFR, MAPK1, and MAPK14 as the core targets." (PMID 36523421, 2022). "Several inflammatory mediators, such as NF-kB, TNF-α, and MMP-9, were observed to be higher in chronic obstructive pulmonary disease (COPD) patients than in healthy controls and were reduced after treatment with RSV." (PMID 35056739, 2022). "Soluble uric acid exerts an inflammation‐stimulatory effect and induced the production of tumor necrosis factor α (TNFα), interleukin (IL)‐6, and IL‐1β,25 it also involved in the lung injury, COPD (chronic obstructive pulmonary disease), and EP (eosinophilic pneumonia)." (PMID 34655117, 2021). "Chronic obstructive pulmonary disease (COPD) significantly increases the expression of tumor necrosis factor (TNF)-like weak inducer of apoptosis (TWEAK), then increases the proportion of type 1 muscle fibers and decreases the proportion of type 2 muscle fibers." (PMID 33553177, 2021). "For example, patients with chronic obstructive pulmonary disease (COPD) with increased levels of Il-6, Il-8, TNF-α demonstrated decreased levels of SQSTM1/p62 in PBMCs." (PMID 30633777, 2019). "In rats with chronic obstructive pulmonary disease (COPD), TNF-α and IL-1β levels in the bronchoalveolar lavage fluid decreased after electroacupuncture." (PMID 28069040, 2017). "Carriers of the GG genotype of TNF-α-238 were characterized by low production of TNF-α by the peripheral blood mononuclear cells and in the sputum of chronic obstructive pulmonary disease patients." (PMID 26572151, 2016). "TST led to significant development of cold allodynia; mechanical and heat hyperalgesia; dynamic mechanical allodynia; functional deficit in walking along with rise in the levels of TBARS, TNF-α, GSH and Nitrite." (PMID 24499201, 2013). "In ASMC from people with chronic obstructive pulmonary disease (COPD), TNF-α induced CXCL10 via NF-κB activation, whereas IFNγ only induced a weak activation of NF-κB and activated STAT-1 as well, but not AP-1." (PMID 23034049, 2012). "In a chronic obstructive pulmonary disease (COPD) mouse model, CPT alleviated lung injury by activating the Keap1/Nrf2 pathway to reduce ROS levels, suppress NF-κB signaling, and lower TNF-α concentrations in pulmonary tissue serum, thereby mitigating inflammation." (PMID 41154678, 2025). "In addition, Wnt5a is reported to be increased in experimental and human chronic obstructive pulmonary disease (COPD) and to induce production of inflammatory cytokines such as IL-6 and TNF-α." (PMID 38062395, 2023). "Furthermore, another study on patients with chronic obstructive pulmonary disease by Rubing Mo and collaborators found that LPS induces lncRNA GAS5 expression and release of IL-2, IL-6, IL-10, and TNF-α." (PMID 37047453, 2023). "Nesfatin-1 levels in plasma from chronic obstructive pulmonary disease (COPD) patients are correlated with plasma levels of interleukin-6 (IL-6), interleukin-8 (IL-8), and tumor necrosis factor-α (TNF-α), implying that nesfatin-1 acts as a novel inflammatory factor in COPD patients." (PMID 36008865, 2022). "A previous study have reported that the expression and secretion of MMP-12 can be regulated by IL-1β and TNF-α in human airway smooth muscle cells, and thereby participated in diseases of the airway, such as chronic asthma or chronic obstructive pulmonary diseases (COPD)." (PMID 33935718, 2021). "The most recent finding examined the preventative effects of crocin supplementation on blood levels of IL-6 and TNF-α, exercise ability, and pulmonary function tests (PFT) in Chronic obstructive pulmonary disease (COPD) patients." (PMID 40154100, 2025).
chronic obstructive pulmonary disease (continued). "Patients with chronic obstructive pulmonary disease (COPD) have been found to have decreased SOCS5 levels, which underpins heightened levels of IL-1β and TNFα." (PMID 39676878, 2024). "RSV also improved lung histological damage and decreased pro-inflammatory cytokines (IL-6, IL-17, TNF-α, and TGF-β) in cigarette smoke chronic obstructive pulmonary disease (COPD) animals." (PMID 37229273, 2023). "In chronic obstructive pulmonary disease (COPD), activation of ERK produces pro-inflammatory cytokines, such as TNF-α, IL-1β, IL-6 and IL-8." (PMID 35889800, 2022). "Furthermore, in patients with chronic obstructive pulmonary disease (COPD) activation of neutrophils, NK cells, Th17 cells, Th2 cells, Th1 cells, dendritic cells, macrophage and TNFα secreting cells can be induced by overexpression of ACE2 leading to a severe inflammatory response." (PMID 34359894, 2021). "Chronic obstructive pulmonary disease (COPD) is “the third killer” in the worldwide public health problem characterized by progressive airflow limitation, progressive lung inflammation and increases in the levels of some inflammatory mediators such as MMP-9, TNF-α and IL-8." (PMID 30909565, 2019). "Tumor necrosis factor-alpha (TNF-α) is a potent pro-inflammatory mediator and its expression is up-regulated in chronic obstructive pulmonary disease (COPD)." (PMID 27911957, 2016). "PTX3 expression is rapidly induced by proinflammatory cytokines, such as TNF-α and IL-1β, and PTX3 has thus been suggested to be a biomarker in inflammation-related diseases such as chronic obstructive pulmonary disease (COPD), hepatocellular carcinoma and liver fibrosis." (PMID 38243273, 2024).
juvenile idiopathic arthritis (193 papers, 2005 to 2026). Juvenile idiopathic arthritis (JIA) is the term used to describe a group of inflammatory articular disorders of unknown cause that begin before the age of 16 and last over 6 weeks. "Studies on pediatric patients with IBD and juvenile idiopathic arthritis have identified infusion-related reactions as significant AEs associated with anti-TNF therapy, particularly IFX." (PMID 39861147, 2025). "Inhibitors of TNFα have been successfully used in the treatment of rheumatoid, and juvenile arthritis for several years." (PMID 40140815, 2025). "Central to the pathogenesis of juvenile idiopathic arthritis is immune dysregulation, which leads to excessive production of proinflammatory cytokines (TNF-α, IL-1, IL-6, IL-17)." (PMID 41465591, 2025). "This study provides valuable insights into the outcomes of anti-TNF-α therapy withdrawal in a large cohort of children with juvenile idiopathic arthritis (JIA)." (PMID 41153616, 2025). "Adalimumab, a TNF-alpha inhibitor, is approved to treat juvenile idiopathic arthritis (JIA), helping control disease activity and reduce flare frequency." (PMID 39940955, 2025). "This case illustrates a TNF-α inhibitor-induced sarcoid-like reaction with pulmonary involvement in a patient with well-controlled juvenile idiopathic arthritis on adalimumab." (PMID 40585695, 2025). "Currently, there are five biologic agents targeting TNFα that are approved for treating various conditions such as rheumatoid arthritis, juvenile idiopathic arthritis (JIA), psoriatic arthritis, inflammatory bowel disease and ankylosing spondylitis." (PMID 39157460, 2024). "The second individual was significantly immunosuppressed with a TNF inhibitor for juvenile arthritis, primary immunodeficiency, and neurological co-morbidities, travelling to Pakistan for a mass gathering." (PMID 38616263, 2024). "On the other hand, anakinra was marginally effective in two female patients with established diagnoses of juvenile idiopathic arthritis, aged approximately 6 and 12 years, who were partially responsive to anti-TNF treatment." (PMID 39334678, 2024). "Proinflammatory CD4+ cells with a similar BHLHE40+ phenotype have been identified in the joints of patients with juvenile arthritis and these cells expressed GM-CSF, TNF-α, and IFN-γ." (PMID 37751304, 2023). "A systematic literature review was conducted to summarize efficacy and safety data from studies that evaluated tumor necrosis factor inhibitors in patients with juvenile idiopathic arthritis (JIA)." (PMID 36829225, 2023). "We sought to evaluate the effectiveness of anti-tumor necrosis factor-α (TNF-α) therapy using the inflammatory indicators, Juvenile Arthritis Disease Activity Score 27 (JADAS27) and magnetic resonance imaging (MRI)." (PMID 37303752, 2023). "The use of etanercept, a TNF inhibitor, has been shown to reduce MMP-9 levels in children with polyarticular juvenile idiopathic arthritis, corroborating the role of TNF in MMP-9 production." (PMID 36311773, 2022). "We assessed the effect of 24-month anti-tumor necrosis factor alpha (TNF-α) treatment on the remodeling of the cartilage extracellular matrix (ECM) in patients with juvenile idiopathic arthritis (JIA)." (PMID 35407621, 2022). "Anti-tumor necrosis factor (TNF) drugs have improved the prognosis for juvenile idiopathic arthritis (JIA) significantly." (PMID 33926495, 2021). "The anti-TNF-α mAb biologics (etanercept and adalimumab) have both been shown to preferentially suppress Th17/Th1 cells and Th17 cell plasticity in vivo in juvenile idiopathic arthritis." (PMID 34502490, 2021). "Approximately 30 % of juvenile idiopathic arthritis (JIA) patients fail to respond to anti-TNF treatment." (PMID 26249667, 2015). "Anti-tumor necrosis factor (TNF) therapy was a breakthrough in managing juvenile idiopathic arthritis (JIA)." (PMID 26047099, 2015).
juvenile idiopathic arthritis (continued). "Anti-TNF agents have proven efficacy in children with severe juvenile idiopathic arthritis (JIA) who are unresponsive to standard therapy." (PMID 23641813, 2013). "This IFN-β-regulated gene profile is interesting with respect to similarities to the patterns that have been identified in patients with SLE and in patients with juvenile arthritis treated with anti-TNF-α, and in mouse models of SLE." (PMID 17490473, 2007). "Moreover, our experience suggests that anti-TNFα is an effective option in CF patients affected by juvenile idiopathic arthritis, and is even safe for children receiving a triple CFTR modulator." (PMID 36902517, 2023). "Furthermore, some juvenile rheumatoid arthritis patients developed MS-like demyelination during anti-TNF therapy." (PMID 34305946, 2021). "Long-term evaluation of cardiac function in juvenile idiopathic arthritis under anti-TNF therapy." (PMID 33295472, 2020). "Whether tumor necrosis factor alpha (TNF-α) gene polymorphisms (SNPs) influence disease susceptibility and treatment of patients with juvenile idiopathic arthritis (JIA) is presently uncertain." (PMID 23133455, 2012). "TNF-α is elevated in both serum and synovial fluid of children with juvenile idiopathic arthritis." (PMID 19200377, 2009). "Although the introduction of TNF biological blockers into clinical practice has significantly improved the treatment of inflammatory conditions such as IBDs and juvenile idiopathic arthritis, patients treated with these agents may experience LoR and relapse of the disease." (PMID 40284416, 2025). "TNF inhibitors (TNFi), used to treat patients with juvenile idiopathic arthritis (JIA), do not only dampen inflammation, but they have been shown to also inhibit the germinal center response and, thus, to decrease the frequency of MBCs." (PMID 37848930, 2023). "• Tumor necrosis factor-alpha (TNFα) is elevated in the serum and the synovial fluid in children with juvenile idiopathic arthritis (JIA)." (PMID 37046333, 2023). "Drugs that target TNF and its receptor are approved and used in a wide variety of diseases including RA, juvenile idiopathic arthritis (JIA), AS, axial spondyloarthritis (SpA), PS, psoriatic arthritis (PsA), IBD, and Behcet’s disease (BD)." (PMID 36451227, 2022). "Etanercept is the first and most important tumor necrosis factor (TNF) inhibitor in the treatment of MTX-resistant juvenile idiopathic arthritis (JIA)." (PMID 32848772, 2020). "In juvenile idiopathic arthritis (JIA), the most common rheumatoid disorder in pediatrics, an elevation of proinflammatory cytokines, such as IL-1β, IL-6, IL-8, or TNF-α, has been demonstrated in both the serum and synovial fluid of patients with JIA." (PMID 31118902, 2019). "Around one-third of patients with juvenile idiopathic arthritis (JIA) fail to respond to first-line MTX or TNF therapy, with even fewer achieving ≥ American College of Rheumatology Pediatric 70% criteria for response (ACRpedi70)." (PMID 30828327, 2019). "Biologics treatment with antitumour necrosis factor alpha (TNFα) is efficacious in patients with juvenile idiopathic arthritis (JIA)." (PMID 31540934, 2019). "The purpose of the study was to evaluate the clinical and magnetic resonance imaging (MRI) outcome of cervical spine arthritis in children with juvenile idiopathic arthritis (JIA), who received anti-TNFα early in the course of cervical spine arthritis." (PMID 28506237, 2017). "Also, anti-TNFα therapy seems able to restore CPC number in juvenile arthritis." (PMID 26241902, 2015). "The study is aimed to evaluate body composition and bone status in adolescent and adult patients with active juvenile idiopathic arthritis (JIA) untreated with tumor necrosis factor alpha inhibitors." (PMID 24558956, 2014). "Therefore, in this study, we explored juvenile idiopathic arthritis [JIA] as such an extraintestinal paediatric diagnosis also treated with anti-TNF." (PMID 37527838, 2024).